GFI1 (growth factor independent 1 transcriptional repressor)
Diseases named in the same sentence as GFI1 in open-access papers (continued):
Sharing a sentence is not in itself a finding about the gene and the disease.
prostate carcinoma (3 papers, 2019 to 2021). A carcinoma that arises from epithelial cells of the prostate gland. "Finally, Gfi1 epigenetic silencing could be a promising biomarker for prostate cancer progression because it is associated with shorter disease-free survival." (PMID 32630147, 2020). "Gfi1 was hypermethylated in the three prostate cancer cell lines analyzed and was unmethylated in normal lymphocytes." (PMID 32630147, 2020). "Our data also showed that Gfi1 methylation implied a worse disease-free survival of prostate cancer patients suggesting Gfi1 epigenetic silencing as a promising biomarker for prostate cancer progression." (PMID 32630147, 2020). "In a previous study showing a DNA hypermethylation profile for prostate cancer we found Gfi-1 hypermethylated in 37% of the cases and unmethylated in the normal tissues analyzed." (PMID 32630147, 2020). "In a previous study showing the gene hypermethylation profile of prostate cancer, we found gfi1 hypermethylated in 37% of the tumor samples." (PMID 32630147, 2020). "Finally, analyzing clinical follow yielded Gfi1 methylation implied a worse disease-free survival of prostate cancer patients (log-rank, p = 0.0161), suggesting Gfi1 epigenetic silencing as a promising biomarker for prostate cancer progression." (PMID 32630147, 2020). "In addition, the data from the immunohistochemistry experiments showed a significant decrease of Gfi1 expression in prostate cancer tissues respect normal prostate and normal-adjacent tissue suggesting a direct link between Gfi1 methylation and expression." (PMID 32630147, 2020). "In addition, Gfi1 was more frequently methylated in prostate cancer samples with Gleason > 8 (48%) than in samples with Gleason ≤ 7 (22%) (p = 0.0213)." (PMID 32630147, 2020). "Although more studies with a larger number of samples may be necessary, our data indicated that Gfi1 methylation could be a good biomarker for prostate cancer progression." (PMID 32630147, 2020).
Sepsis (3 papers, 2017 to 2025). Sepsis is defined as life-threatening organ dysfunction caused by a dysregulated host response to infection. "Uncontrolled release of these cytokines in Gfi1-null mice lead to sepsis and rapid death from infection." (PMID 34868007, 2021). "We assayed Ly6G and Ly6C expression in different MDSC subsets obtained from Gfi1:GFP knock-in mice with sepsis following CLP challenge." (PMID 28337051, 2017). "Although granulocytes and monocytes can be distinguished in Gfi1:GFP knock-in mice in this mouse sepsis model, it would be more helpful to be able to distinguish them in wild-type mice." (PMID 28337051, 2017). "To confirm that sepsis induces expansion of neutrophil-like monocytes, we performed CLP on Gfi1-tdTomato mice and found that Gfi1hiFSChi monocytes were significantly increased in post-CLP mice." (PMID 40475424, 2025). "We challenged growth factor independent 1 transcription repressor green fluorescent protein (Gfi1:GFP) knock-in reporter mice with cecal ligation and puncture surgery and found that CD11b+Ly6GlowLy6Chigh MDSCs in this sepsis model comprised both monocytic and granulocytic MDSCs." (PMID 28337051, 2017).
small cell lung carcinoma (3 papers, 2009 to 2018). Small cell lung cancer (SCLC) is a highly aggressive malignant neoplasm, accounting for 10-15% of lung cancer cases, characterized byrapid growth, and early metastasis. "Also, GFI1 acts as an oncogene in human small cell lung cancer (SCLC), the deadliest neuroendocrine tumor." (PMID 19737418, 2009). "Gfi-1 co-expression with neuroendocrine markers, including the DCV-related protein chromogranin A and calcitonin peptide, in small cell lung carcinoma (SCLC) strongly suggests its involvement in the maintenance of the neoplastic phenotype of neuroendocrine lung tumors." (PMID 19343207, 2009).
T-cell leukemia (3 papers, 2013 to 2018). A malignant disease of the T-lymphocytes in the bone marrow, thymus, and/or blood. "Growth factor independent 1 (Gfi1) is a transcriptional repressor originally identified as a gene activated in T-cell leukemias induced by Moloney-murine-leukemia virus infection." (PMID 24068942, 2013). "We also employed two cultured human cell models: (i) SupT1 T-cell lymphoblasts ectopically overexpressing GFI1 to determine the effects of increased GFI1 expression and (ii) a Jurkat T-cell leukemia line in which GFI1 was knocked-out using a Crispr/Cas9 strategy." (PMID 29651020, 2018).
asthma (2 papers, 2024 to 2025). "Genetic variants annotated to GFI1 were related to coronary artery disease, white blood cell measures, fat measures, multiple sclerosis, being a morning person, height, lung function, and asthma, eczema, and allergy related measures." (PMID 41136745, 2025). "GFI-1 plays a critical role in lymphoid differentiation, which could be the reason for its association here due to the large influence the immune system can play on lung functionality and, more generally, asthma as a whole." (PMID 39488688, 2024).
atherosclerosis (2 papers, 2022 to 2023). A disease characterized by the build-up of fatty material and calcium deposition in the arterial wall resulting in partial or complete occlusion of the arterial lumen. "In a sample of African-Americans, DNA methylation of AHRR, GFI1, and LRRC52 were associated with atherosclerosis after adjusting for cardiovascular diseases risk factors." (PMID 38031118, 2023). "After adjusting for CVD risk factors, four CpGs (cg05575921(AHRR), cg09935388 (GFI1), cg21161138 (AHRR), and cg18168448 (LRRC52)) were associated with multi-site atherosclerosis (FDR < 0.1)." (PMID 35039093, 2022).
B cell lymphomas (2 papers, 2013 to 2017). "Gfi1 was originally identified as a frequent target of proviral insertion in T and B cell lymphomas, which resulted in the activation of Gfi1 at both the transcriptional and post-transcriptional levels." (PMID 24023884, 2013).
cervical cancer (2 papers, 2022 to 2024). A primary or metastatic malignant neoplasm involving the cervix. "For example, it was found that lncRNA HCG11 (human leukocyte antigen complex group 11) could enhance the expression of GFI1 (growth factor independence-1) to suppress the proliferation and invasion of cancer cells, functioning as a regulator of miR-942-5p via sponging in cervical cancer." (PMID 35356220, 2022).
diabetes (2 papers, 2009 to 2021). "To assess the role of Gfi1 in the pathogenesis of diabetes, we challenged Gfi1-deficient mice with two models of induced hyperglycemia: long-term high-fat/high-sugar feeding and streptozotocin injections." (PMID 34831029, 2021). "This hormone exerts a paracrine action on the pancreatic endocrine cells, protecting Gfi1 mutant mice against STZ-induced diabetes." (PMID 34831029, 2021). "In other words, inhibiting Gfi1 could be extremely beneficial for both type 1 diabetes mellitus and type 2 diabetes mellitus as it prevents diet-induced hyperglycemia while sustaining the survival of β cells." (PMID 34831029, 2021). "For human diseases that might benefit from increased neurosecretion, such as diabetes mellitus, targeted knockdown of Gfi-1 function represents a potential therapeutic target." (PMID 19343207, 2009). "As important was the finding that animals lacking Gfi1 in their pancreata were protected from streptozotocin-mediated diabetes, most likely due to the misexpression of Ghrelin in acinar cells." (PMID 34831029, 2021).
gastric cancer (2 papers, 2021 to 2022). A primary or metastatic malignant neoplasm involving the stomach. "It has been also reported that the phosphorylated GFI1 is a substrate of SCF-type ubiquitin ligase FBXW7 in gastric cancer cells." (PMID 34351909, 2021). "In addition, ubiquitin ligase FBXW7 has been shown to mediate the phosphorylation-dependent ubiquitination and degradation of GFI1 in gastric cancer cells." (PMID 34351909, 2021). "Especially, with regard to EMT process, several articles demonstrated the important roles of m6A regulation on SNAI1 in HeLa and HepG2 cells, GFI1 and ZMYM1 in gastric cancer cells, AXL in ovarian cancer cells, and ZBTB1 in bronchial epithelial cells." (PMID 36183833, 2022).
glioma (2 papers, 2021 to 2023). A benign or malignant brain and spinal cord tumor that arises from glial cells (astrocytes, oligodendrocytes, ependymal cells). "A recent study reported that MEIS1 inhibits apoptosis of glioma cells by upregulating GFI1 expression." (PMID 36834999, 2023).
hepatocellular carcinoma (2 papers, 2020 to 2022). A malignant tumor that arises from hepatocytes. "For instance, LINC00675 inhibited hepatocellular carcinoma metastasis by reducing miR-942-5p and promoting GFI1 expression." (PMID 36087568, 2022).
Hyperglycemia (2 papers, 2021 to 2023). An increased concentration of glucose in the blood. "In fact, Gfi1-deficient mice were found resistant to diet-induced hyperglycemia, appearing normoglycemic even after long-term high-fat/high-sugar diet." (PMID 34831029, 2021). "Intrigued by these observations, we decided to study the effects of Gfi1 loss of function using experimental models of induced hyperglycemia." (PMID 34831029, 2021). "Interestingly, the decreased efficiency of carbohydrates absorption protects Gfi1 mutant mice against HFCD-induced hyperglycemia." (PMID 34831029, 2021).
latent infection (2 papers, 2024 to 2025). "Thus, continuous expression of GFI1 is crucial for sustaining persistent CD8+ T cell responses in chronic and latent infections." (PMID 40374731, 2025). "Hyper-methylated in PcG targeted transcription factor binding sites might release GFI1, repress MIEP, and maintain CMV latent infection from entering the lytic phase." (PMID 39360678, 2024).
lupus (2 papers, 2019 to 2020). "In the case of lupus, in mice model knockdown of Gfi1 developed this entity which might be also associated with the negative regulation of TLR7." (PMID 32899152, 2020). "Moreover, it has been proved that Gfi1-deficient mice develop autoimmunity and particularly B cell-dependent autoimmunity like lupus." (PMID 32899152, 2020). "Moreover, mice lacking Gfi1 have recently been reported to develop a TLR7-dependent lupus-like phenotype, which the authors showed to involve excess NFκB signaling." (PMID 31659207, 2019).
ovarian carcinoma (2 papers, 2022). A malignant neoplasm originating from the surface ovarian epithelium. "GFI1 was also frequently expressed in human primary breast and ovarian cancer cells." (PMID 35819844, 2022).
schizophrenia (2 papers, 2019 to 2025). A major psychotic disorder characterized by abnormalities in the perception or expression of reality. "However, several VMPs exhibited opposite patterns of variance between blood and brain regions, including some within the GRIK3, GFI1, ADRB3 and MND1 genes, amongst others, indicating that some schizophrenia associated VMPs may exhibit divergent variance patterns between the periphery and brain." (PMID 39271751, 2025).
abscess (1 paper, 2018). An inflammatory process characterized by the accumulation of pus within a newly formed tissue cavity which is the result of a bacterial, fungal, or parasitic infection or the presence of a foreign body. "Both studies mention infections and/ or abscess formation in Gfi1-ko/ko mutants but do not specify the pathogen load and weaning schedules of their SPF facilities." (PMID 29879182, 2018).
brain tumors (1 paper, 2020). "Among all the tested combinations, we observed reduced mice survival with Gfi1 + c-MYC (GM) and Otx2 + c-MYC (OM) genes overexpression and formation of brain tumors." (PMID 31996670, 2020).
cardiomyopathy (1 paper, 2025). A disease of the heart muscle or myocardium proper. "Additionally, Gfi1's salvaging impact on cell survival was also unveiled in other fields, such as cardiomyopathy and otopathy." (PMID 40787173, 2025).
colitis (1 paper, 2021). Inflammation of the colon. "In our setting, we indeed found that the mRNA levels of goblet cell maturation-related transcription factors Gfi1, Spdef, and Klf4 were higher in Gsdmd-deficient mice than in WT mice during colitis." (PMID 34721422, 2021).
colorectal adenocarcinoma (1 paper, 2019). The most common type of colorectal carcinoma. "Colorectal adenocarcinoma cases were analysed for associations between GFI1 or TNFRSF11A mRNA expression and clinicopathological features." (PMID 30858927, 2019).
colorectal tumour (1 paper, 2019). "This study then utilized RNAscope® to quantify mRNA expression of candidate prognostic markers GFI1 and TNFRSF11A, and analysed their association with clinicopathological features from FFPE colorectal tumour tissue." (PMID 30858927, 2019). "Having established RNAscope® as a technical comparable method to immunohistochemistry, this study successfully utilized RNA in situ hybridisation (RNAscope®) to quantify mRNA expression of candidate prognostic markers GFI1 and TNFRSF11A from FFPE colorectal tumour tissue." (PMID 30858927, 2019).
conduct disorder (1 paper, 2018). A disorder diagnosed in childhood or adolescence age group characterized by aggressive behavior, deceitfulness, destruction of property or violation of rules that is persistent and repetitive, and within a one year period. "Despite the small size of the population studied, DNA methylation at AHRR and GFI1, but not at CYP1A1, were shown to be related to the severity of conduct disorder and ADHD in children of smoking mothers." (PMID 29618728, 2018).
cytomegalovirus infection (1 paper, 2025). A herpesvirus infection caused by Cytomegalovirus. "Thus, GFI1 acted to epigenetically repress the transcriptional landscape of CD8+ T cells and promote inflationary T cell responses to cytomegalovirus infection." (PMID 40374731, 2025).
glaucoma (1 paper, 2020). Increased pressure in the eyeball due to obstruction of the outflow of aqueous humor. "Population specific distribution of GFI1 enhancer alleles may predispose certain ethnic groups to glaucoma." (PMID 33092545, 2020).
Immunodeficiency (1 paper, 2018). Failure of the immune system to protect the body adequately from infection, due to the absence or insufficiency of some component process or substance. "Normal development upon weaning suggests that maternal passive immunity via milk-derived secretory IgA at least temporally compensates for the immunodeficiency due to Gfi1 ablation." (PMID 29879182, 2018).
laryngeal carcinoma (1 paper, 2018). Carcinoma that arises from the laryngeal epithelium. "Increased methylation levels of promoters of TOP2A (DNA topoisomerase II alpha), PLXDC2 (plexin domain containing 2), ETNK2 (ethanolamine kinase 2), GFI1 (growth factor independent 1 transcriptional repressor), and IL12B (interleukin 12B) were detected in radioresistant laryngeal cancer cells." (PMID 29439529, 2018).
lung adenocarcinoma (1 paper, 2022). A carcinoma that arises from the lung and is characterized by the presence of malignant glandular epithelial cells. "Analysis of The Cancer Genome Atlas also revealed the positive correlation between GFI1 and RASGRP2 in lung adenocarcinomas." (PMID 35819844, 2022).
neuroendocrine carcinoma (1 paper, 2009). A malignant neuroendocrine neoplasm composed of cells containing secretory granules that stain positive for NSE and chromogranin. "Further studies are required to look for mutations in neuroendocrine pathway genes and to examine directly the role of Gfi-1/PAG-3 and IA-2 in SCLC and related neuroendocrine cancers." (PMID 19343207, 2009).
Osteopenia (1 paper, 2018). Osteopenia is a term to define bone density that is not normal but also not as low as osteoporosis. "To assess the cellular origin of osteopenia after Gfi1 ablation, we determined the numbers of osteoblasts and osteoclasts by histomorphometry." (PMID 29879182, 2018). "Early (nonSPF) and late (SPF+nonSPF) pathogen exposure of Gfi1-ko/ko mice results in osteoporosis and osteopenia, respectively." (PMID 29879182, 2018). "Thus, SPF+nonSPF Gfi1-ko/ko mice develop osteopenia due to increase bone cell activity that likely favors bone resorption by osteoclasts." (PMID 29879182, 2018).
osteoporosis (1 paper, 2018). A condition of reduced bone mass, with decreased cortical thickness and a decrease in the number and size of the trabeculae of cancellous bone (but normal chemical composition), resulting in increased fracture incidence. "Early high pathogen load (nonSPF) causes osteoporosis in Gfi1-ko/ko mice marked by an extreme systemic inflammatory response, diminished osteoclast as well as osteoblast numbers, and low bone cell activity." (PMID 29879182, 2018). "Gfi1-ko/ko mice grown under conditions of high pathogen exposure (nonSPF) exhibit growth retardation associated with osteoporosis and premature death immediately after weaning." (PMID 29879182, 2018). "We thus speculate that extreme cytokine levels compromise bone and immune cell viability and/ or function leading to osteoporosis and reduce survival rates of nonSPF Gfi1-ko/ko mice." (PMID 29879182, 2018).
otitis media (1 paper, 2012). Inflammation of the anatomical structures of the middle ear, which is most often caused by an infectious process. "The effective blockage of the Atoh1, SPDEF, or GFI1 expression in the early phase of disease may be a new strategy for treating intractable otitis media." (PMID 22518155, 2012). "There is no report to discuss the involvement of Atoh1, GFI1, or Spdef in otitis media." (PMID 22518155, 2012).
Parkinson disease (1 paper, 2009). A progressive degenerative disorder of the central nervous system characterized by loss of dopamine producing neurons in the substantia nigra and the presence of Lewy bodies in the substantia nigra and locus coeruleus. "Our findings are impelling to explore inverse regulation of BDNF and SNCA genes by GFI1 and MEF2 in neurons generally and in Parkinson's disease models in particular." (PMID 19737418, 2009).
Rectal prolapse (1 paper, 2023). Protrusion of the rectal mucous membrane through the anus. "The expression of Muc2 and goblet cell differentiation factor Gfi1 in the rectum of Per2−/− mice was also higher than that of WT mice, suggesting that the occurrence of rectal prolapse in Per2−/− mice is not related to impairment of intestinal mucosal immunity." (PMID 37660913, 2023).
rectal tumours (1 paper, 2019). "Significant associations between negative GFI1 mRNA expression and age groups (CI 0.55–12.27, P = 0.05), grade (CI 0.003–0.91, P = 0.05), left-sided tumours (CI 1.21–21.45, P = 0.02), and rectal tumours (CI 0.07 – 2.26, P = 0.04) were observed by univariate analysis." (PMID 30858927, 2019).
Splenomegaly (1 paper, 2019). Abnormal increased size of the spleen. "However, over an observation period of 300 days, almost all Gfi1 KD mice died with symptoms such as weight loss and splenomegaly, whereas almost all Gfi1 KO mice and all WT or KI animals survived this observation period." (PMID 29925903, 2019).
viral infection (1 paper, 2025). "In conclusion, this study reveals an important function for GFI1 in maintaining CD8+ T cell persistence following chronic viral infection." (PMID 40374731, 2025). "This highlights the requirement for GFI1 expression in CD8+ T cells throughout the course of chronic viral infection to generate immune protection." (PMID 40374731, 2025). "GFI1 was found to be crucial for maintaining CD8+ T cell persistence during chronic viral infection." (PMID 40374731, 2025). "Given the downregulation of EOMES in CD8+ TSCM cells and reduced chromatin accessibility at the Eomes locus in GFI1ΔCD8 CD8+ TM cells, we examined the requirement for GFI1-mediated EOMES in maintaining the persistence of CD8+ T cells following chronic viral infection." (PMID 40374731, 2025). "Here, we examined the role of GFI1 in CD8+ TM cell development after acute and chronic viral infection." (PMID 40374731, 2025). "However, the exact role of GFI1 in maintaining TM cells following acute and chronic viral infection is not understood." (PMID 40374731, 2025).